BMP8B (bone morphogenetic protein 8b)
Description:
Induces cartilage and bone formation. May be the osteoinductive factor responsible for the phenomenon of epithelial osteogenesis. Plays a role in calcium regulation and bone homeostasis (By similarity).
Synonyms: OP-2; BMP8; OP2
Tractability: Antibody: UniProt places it where antibodies can reach, with medium confidence; UniProt predicts a signal peptide or a membrane-spanning region; its Gene Ontology location is reachable by antibodies, with medium confidence. PROTAC: ubiquitination databases record sites on it.
Gene: Protein-coding gene on chromosome 1 (39,757,182 to 39,788,865, reverse strand). Ensembl gene ENSG00000116985.
Subcellular location: Secreted
Subcellular location (Human Protein Atlas): Vesicles; Predicted to be secreted
Gene Ontology:
Molecular function: cytokine activity; growth factor activity
Biological process: BMP signaling pathway; negative regulation of cell differentiation; skeletal system development; developmental process
Cellular component: extracellular region
Genetic constraint (gnomAD): Loss-of-function variants: 15 observed, 17.81 expected, observed/expected ratio (o/e) 0.84, 90% interval 0.56 to 1.3. The upper end of that interval is the gene's LOEUF score, 1.3, which puts it in group 5 of 6, group 1 being the genes least tolerant of losing a copy. Missense variants: 232 observed, 287.11 expected, observed/expected ratio (o/e) 0.81, 90% interval 0.73 to 0.9. Synonymous variants: 117 observed, 119.52 expected, observed/expected ratio (o/e) 0.98, 90% interval 0.84 to 1.14.
Homologues: Orthologues: chimpanzee BMP8B (99% identical), macaque BMP8B (96% identical), tropical clawed frog bmp8 (64% identical), zebrafish bmp8a (56% identical). Paralogues in human: BMP8A (98% identical), BMP5 (52% identical), BMP6 (52% identical), BMP7 (52% identical), BMP2 (29% identical), GDF2 (28% identical), GDF6 (28% identical), BMP4 (27% identical), BMP10 (25% identical), GDF7 (25% identical), GDF5 (24% identical), INHBB (22% identical), and 19 more.
Diseases named in the same sentence as BMP8B in open-access papers:
BMP8B is named in the same sentence as 33 diseases in open-access papers, as found by Europe PMC text mining. Sharing a sentence is not in itself a finding about the gene and the disease. The quoted sentences say what the papers report.
Obesity (14 papers, 2012 to 2025). Accumulation of substantial excess body fat. "Bmp8b knockout mice display impaired thermogenesis capacity and are susceptible to diet-induced obesity." (PMID 39680603, 2024). "Conversely, BMP8B-deficient mice exhibit altered brown adipose tissue with impaired thermogenesis and susceptibility to diet-induced obesity." (PMID 31096638, 2019). "In the context of obesity, BMP8B has been shown to play a protective role by enhancing BAT activity, for example, BMP8B knockout mice exhibit reduced thermogenesis and increased susceptibility to diet-induced obesity, whereas central BMP8B treatment enhanced sympathetic activation of BAT." (PMID 41292047, 2025). "The underlying mechanism is that (i) BMP8B treatment induces a decrease in BMP receptors in VMH of obesity; (ii) BMP8B loses the ability to inhibit AMPK." (PMID 39872218, 2024). "Like many metabolically favorable hormones, obesity also induces resistance to central action of BMP8B." (PMID 39872218, 2024). "Conceivably, disruption of the inhibitory regulation of BMP8B on adipogenesis is a potential contributing factor to the development of obesity." (PMID 38201894, 2023). "The bone morphogenetic protein-8B (BMP8B) has been shown to be expressed in brown adipose tissues and the hypothalamus and to affect thermogenesis and susceptibility to diet-induced obesity." (PMID 31096638, 2019). "Our findings demonstrated that WDR4 drives mitophagy through enhancing BMP8B expression by increasing its translation efficiency by tRNA m7G modification, thereby promoting adipocyte browning and improving metabolic health in the context of obesity." (PMID 41292047, 2025). "Overall, BMP8B, derived from both adipocytes and hypothalamus, functions through autocrine and paracrine signaling, synergistically activating thermogenic adipocytes and protecting against diet-induced obesity in females." (PMID 39872218, 2024). "As a result, female mice deficient in BMP8B display impaired thermogenesis and reduced metabolic rate, causing obesity, whereas male mice lack of BMP8B exhibit no phenotype in energy metabolism." (PMID 39872218, 2024). "Our findings suggest that increasing the level of BMP8B or enhancing BMP8B signaling may hold potential in combatting obesity." (PMID 38201894, 2023). "On the basis of previous studies describing BMP8B expression in brown adipose tissue and the hypothalamus as a critical regulator of thermogenesis and a modulator of obesity, the focus of the present study was on NAFLD and fatty acid-induced alterations in hepatocytes." (PMID 31096638, 2019). "However, the obesity phenotype is only observed at thermoneutrality (30°C) but not at 22°C in the Dio2 deficient mice, whereas it occurs at lower temperatures (~25°C) in the OT, OTR and Bmp8b deficient mice." (PMID 39345420, 2024). "Thus, induction of BMP8b by marigold SFE could be an interesting strategy for tackling obesity and for promoting metabolic health." (PMID 32039173, 2019). "For instance, YTHDF1 enhances the translation of bone morphogenetic protein 8b (Bmp8b) mRNA by specifically binding to its 3′ untranslated region (3′UTR), thereby facilitating inguinal WAT beiging and alleviating obesity." (PMID 40729009, 2025). "Several recently discovered batokines, such as FGF21, NRG4, BMP8b, CXCL14, or adiponectin have been shown to exert a protective role against obesity by enhancing beiging of WAT, lipolysis, sympathetic innervation, or polarization of M2 macrophages." (PMID 34708041, 2021). "In this regard, knockout BMP8b animals become more obese than wild animals when fed an HF diet, while the ablation of PPAR-α also turns rodents more prone to obesity due to the reduced ability to use lipids as fuel to the thermogenesis." (PMID 29351550, 2018). "It is likely that BMP8B serves as a negative feedback control at the autocrine level to restrain adipogenesis because obesity leads to an increase in BMP8B." (PMID 38201894, 2023).
Obesity (continued). "Thus, BMP8b and NRG4 can be considered as interconnected regulators of neuro-vascular remodeling in AT and are potential therapeutic targets in obesity." (PMID 30478315, 2018).
gastric cancer (7 papers, 2013 to 2025). A primary or metastatic malignant neoplasm involving the stomach. "Using DNA microarray analysis, the present study identified bone morphogenetic protein 8B (BMP8B) as a secreted signaling molecule in the bone marrow that was associated with the metastatic disease of human gastric cancer." (PMID 24137334, 2013). "High BMP8B expression in the bone marrow was associated with the diffuse type of gastric cancer (P=0.009), lymph node metastasis (P=0.009), liver metastasis (P=0.044) and peritoneal dissemination (P<0.001)." (PMID 24137334, 2013). "In the current analyses, the presence of metastatic gastric cancer in the lymph nodes, liver and peritoneum was more closely associated with high expression levels of BMP8B in the bone marrow compared with those in the peripheral blood." (PMID 24137334, 2013). "Moreover, decreased H3K9Ac at the BMP8B promoter region has been associated with histological diffuse-type gastric cancer compared to the intestinal-type of this neoplasm." (PMID 31121824, 2019). "The present study initially examined whether the expression levels of BMP8B mRNA in the primary site, peripheral blood and bone marrow samples that were extracted from a large number of gastric cancer patients were associated with metastatic gastric cancer." (PMID 24137334, 2013). "Expression levels of BMP8B are significantly increased in the bone marrow of gastric cancer patients with metastatic disease, consistent with a role of a secreted factor in cancer progression." (PMID 33288848, 2020). "The reduction of H3K9Ac and H4K16Ac expressions at the BMP8B promoter region has been connected with poorly-differentiated gastric cancer in comparison with moderately differentiated tumors." (PMID 31121824, 2019). "Another study showed that the levels of H3K9Ac and H4K16Ac are increased at the promoter region of the bone morphogenetic 8B (BMP8B) gene in gastric cancer." (PMID 31121824, 2019). "In the primary site, a multivariate analysis revealed BMP8B mRNA expression as one of the independent prognostic factors of gastric cancer [hazard ratio (HR), 2.066; 95% CI, 1.132–3.772]." (PMID 24137334, 2013). "BMP8B was strongly expressed in the gastric cancer cells of the primary tumors, with high BMP8B mRNA expression." (PMID 24137334, 2013). "Next, the expression levels of BMP8B mRNA in the tumor samples from the 144 gastric cancer patients were analyzed." (PMID 24137334, 2013). "Further studies are required to investigate the functional roles of BMP8B in metastatic gastric cancer." (PMID 24137334, 2013). "The expression levels of BMP8B in the bone marrow of 355 gastric cancer patients were increased with metastatic disease." (PMID 24137334, 2013). "The BMP8B is also known as a tumor suppressor in cancer of the stomach, ovary and pancreas." (PMID 34680872, 2021). "Furthermore, BMP8B has been shown to promote the progression of pancreatic cancer, while conflicting studies exist regarding its role in gastric cancer." (PMID 31096638, 2019). "Together, these results indicate that tumor-derived BMP8B may affect the bone marrow, leading to metastatic gastric cancer." (PMID 24137334, 2013). "Similarly to AL033527.3, although there was no direct study of this lncRNA in gastric cancer, its possible antisense regulatory target BMP8B is associated with lymph node metastasis, liver metastasis and peritoneal dissemination in GC." (PMID 37408779, 2023). "The BMP8B protein was observed to be expressed by the gastric cancer cells, but not by the stromal cells." (PMID 24137334, 2013).
breast carcinoma (4 papers, 2019 to 2023). "The present study showed BMP8B was significantly increased in breast tumours, while BMP6 and ACVRL1 were decreased in breast cancer tissues." (PMID 37333824, 2023). "BMP8B was significantly active in primary breast cancer, whereas BMP2, BMP4, BMP5, BMP6 and BMP8B were significantly active in liver metastasis." (PMID 37958607, 2023). "BMP8B was significantly active in primary breast cancer, while BMP2, BMP4, BMP5, BMP6, BMP8B were significantly active in liver metastasis." (PMID 31557971, 2019).
osteosarcoma (4 papers, 2009 to 2022). A usually aggressive malignant bone-forming mesenchymal neoplasm, predominantly affecting adolescents and young adults. "BMP9 has been shown to promote the proliferation of osteosarcoma cells, which is similar to this study’s finding that BMP8b was a risk factor in osteosarcoma." (PMID 34342651, 2021). "Therefore, the role of BMP8b in osteosarcoma needs further research." (PMID 34342651, 2021). "For example, like BMP9, bone morphogenetic protein 8b (BMP8b) is a member of the BMP family, and BMP9 and BMP8b may share some identical or similar outcomes in osteosarcoma." (PMID 34342651, 2021).
Hepatic steatosis (3 papers, 2019 to 2025). Steatosis is a term used to denote lipid accumulation within hepatocytes. "Notable batokines include fibroblast growth factor 21 (FGF21), which enhances glucose uptake and lipid oxidation, neuregulin 4 (NRG4), which protects against hepatic steatosis, and bone morphogenetic protein 8b (BMP8b), which enhances the thermogenic capacity." (PMID 40699742, 2025). "The correlation was performed and found that a significant positive correlation exists between the degree of fatty liver and BMP8B levels (r = 0.477; p<0.0001)." (PMID 38127951, 2023). "In this study, we analyzed the expression of BMP8B in an in vitro model of hepatic steatosis as well as in a murine NAFLD model and in liver tissues of NAFLD patients." (PMID 31096638, 2019). "To assess the effect of hepatocellular lipid accumulation on BMP8B expression, we applied an established in vitro model of hepatic steatosis." (PMID 31096638, 2019). "In summary, the present study has newly revealed increased hepatocellular BMP8B expression in liver steatosis and the impact of BMP8B on hepatic steatosis and inflammation, which are critical pathophysiological steps of NAFLD." (PMID 31096638, 2019). "Additionally, subgroup analysis was conducted within NAFL group based on the degree of fatty liver (Grade-1 (n = 32), Grade-2 (n = 28), and Grade-3 (n = 12)) and we observed that circulatory BMP8B levels have shown statistically significant differences among the study groups (p = 0.0002)." (PMID 38127951, 2023). "One such secreted adipokine which is induced by obesity and a high-fat diet and has been recently identified to induce hepatic steatosis and inflammation in the in-vitro and in-vivo steatotic models of NAFLD is BMP8B." (PMID 38127951, 2023). "Future studies are warranted with detailed insight into the molecular mechanisms involved behind the role of elevated BMP8B levels in NASH conditions and its impact on hepatic steatosis and inflammation." (PMID 38127951, 2023).
pancreatic cancer (3 papers, 2017 to 2019). "For this, MiaPaca-2 pancreatic cancer cells were transfected with si-RNA pools against the human BMP8B mRNA (siTOOLs Biotech GmbH)." (PMID 32039173, 2019). "BMP8B has been proposed to act as a tumor suppressor in pancreatic cancer, leading to the inhibition of invasion and tumor growth of pancreatic cancer xenografts." (PMID 32039173, 2019). "Herein, it is demonstrated that marigold SFE induces BMP8b in pancreatic cancer leading to AICD." (PMID 32039173, 2019). "BMP8B mediated pancreatic cancer cell survival and regulated pancreatic cancer progression." (PMID 27902487, 2017).
lymph node metastasis (2 papers, 2013 to 2023). "With regard to the clinicopathological factors, a significant correlation was demonstrated between high BMP8B mRNA expression in the bone marrow and the diffuse type (P=0.009), lymph node metastasis (P=0.009), liver metastasis (P=0.044) and peritoneal dissemination (P<0.001) of the tumors." (PMID 24137334, 2013).
steatosis (2 papers, 2019 to 2023). Increased lipid within the cytoplasm of cells. "Here, BMP8B depletion reduced fatty acid-induced steatosis, while exogenous BMP8B induced lipid accumulation in hepatocytes." (PMID 31096638, 2019). "In a complementary approach, we analyzed the effect of BMP8B suppression on basal as well as fatty acid-induced steatosis in the human hepatoma cell line HepG2." (PMID 31096638, 2019). "Future studies should provide other mechanisms that may influence BMP8B expression in liver tissue other than steatosis." (PMID 38127951, 2023). "Interestingly, combined application of BMP8B and epinephrine equalized the steatosis-inducing effects of the single compounds." (PMID 31096638, 2019). "In this study, we identified hepatocytes as a further source of BMP8B and found that BMP8B expression is further upregulated by lipid accumulation in hepatocytes in vitro as well as in the liver of mice fed with steatosis-inducing Western-type diet and in hepatic tissues of NAFLD patients." (PMID 31096638, 2019). "Furthermore, inhibitory effects of BMP8B on the steatosis-induced downregulation of key enzymes of de novo lipogenesis seem to contribute to its pro-steatotic effect in hepatocytes." (PMID 31096638, 2019). "Together, these data indicate that steatosis induces BMP8B expression in hepatocytes." (PMID 31096638, 2019). "Furthermore, it is interesting that the combined application of BMP8B and epinephrine equalized the steatosis-inducing effects of the single compounds in our in vitro model of hepatocellular steatosis." (PMID 31096638, 2019). "However, and interestingly, our data also give an indication that BMP8B can affect the beta-adrenergic response and the mitochondria membrane potential in a way counteracting steatosis." (PMID 31096638, 2019). "Furthermore, we investigated the effect of BMP8B in functional in vitro models of lipid accumulation and steatosis-induced pro-inflammatory gene expression." (PMID 31096638, 2019). "Still, the steatosis-inducing effect of BMP8B is dominant in hepatocytes in vitro." (PMID 31096638, 2019). "This suggests that, in addition to steatosis, further mechanisms may induce hepatic BMP8B expression, which needs to be evaluated in future studies." (PMID 31096638, 2019). "Next, we analyzed BMP8B expression in an established murine NAFLD model; we have previously shown that mice fed with a steatosis-inducing WTD showed similar pathological changes as those found in NAFLD patients." (PMID 31096638, 2019). "We found that BMP8B expression further increased in patients with NASH as compared with patients with simple steatosis (data not shown)." (PMID 31096638, 2019).
cryptorchidism (1 paper, 2017). The failure of one or both testes of a male fetus to descend from the abdomen into the scrotum during the late part of pregnancy. "Both BMP8B and SMAD4 function in the same signaling pathway, and it is likely that this pathway is involved in the etiology in CAKUT accompanied by cryptorchidism." (PMID 29197384, 2017). "In the present study, non-synonymous SNPs in both BMP8B and SMAD4 loci were found to be common to all patients with CAKUT accompanied by cryptorchidism, suggesting that impairment of the BMP/SMAD signaling pathway was likely involved in the pathogenesis of this condition." (PMID 29197384, 2017).
hepatoma (1 paper, 2019). "Future studies will need to investigate the expression and function of BMP8B in the development and progression of hepatocellular carcinoma." (PMID 31096638, 2019).
Insulin resistance (1 paper, 2012). Increased resistance towards insulin, that is, diminished effectiveness of insulin in reducing blood glucose levels. "Considering that AMPK is already a targetable candidate in peripheral tissues to treat insulin resistance (metformin), the relationship with BMP8B could offer new opportunities for drug design." (PMID 22579288, 2012).
liver diseases (1 paper, 2019). "This suggests that BMP8B also plays a pathophysiological role in other (chronic) liver diseases, which also needs to be addressed in future studies." (PMID 31096638, 2019).
non-alcoholic steatohepatitis (1 paper, 2022). "Other data in experimental models have shown that, despite BMP8B expression is minimal in healthy liver, hepatic BMP8B expression is increased under conditions of non-alcoholic steatohepatitis." (PMID 35402348, 2022).
seminoma (1 paper, 2015). A radiosensitive malignant germ cell tumor found in the testis (especially undescended), and extragonadal sites (anterior mediastinum and pineal gland). "In CIS, seminomas and ECs, expression of BMP8B, BMPR1A /2, SMAD1 /4 and ID1 /2 was detected, while ID3 expression was restricted to ECs." (PMID 26226633, 2015).
Uterine leiomyoma (1 paper, 2018). The presence of a leiomyoma of the uterus. "We describe a potentially deleterious somatic heterozygous mutation in bone morphogenetic protein 8B (BMP8B) gene (c.1139A > G, Tyr380Cys) that was identified in the pulmonary metastasis and was absent from blood and uterine leiomyoma, and may play a facilitating role in the metastasizing of BML." (PMID 29386003, 2018).